MPP7 (MAGUK p55 scaffold protein 7)
Diseases named in the same sentence as MPP7 in open-access papers (continued):
Sharing a sentence is not in itself a finding about the gene and the disease.
cancer (5 papers, 2020 to 2024). A tumor composed of atypical neoplastic, often pleomorphic cells that invade other tissues. "We then explored the prognostic value of MPP7 expression in different types of cancer and determined the gene mutations and phosphorylation of MPP7." (PMID 39224268, 2024). "Further mutations in cancer-related genes included Nav3 (V1129L), Cenpf (D1327E), Muc5ac (A429P), Mpp7 (Q158R), Gas1 (G326R), Maged2 (A473S), Dusp1 (C24R), Ros1 (W1875C), Polr2a (M1102I), Rragd (L385P), and Hoxa9 (insertion of “G” in UTR)." (PMID 32793490, 2020). "The results obtained using various immune deconvolution approaches revealed that MPP7 was significantly related to immune cell infiltration, including cancer-related fibroblasts and CD8+ T cells, in certain tumors." (PMID 39224268, 2024). "The expression level of MPP7 in multiple cancer types in TCGA dataset was analyzed utilizing TIMER2 platform." (PMID 39224268, 2024). "Collectively, these studies indicate that MPP7 is involved in the tumorigenesis of different cancers." (PMID 39224268, 2024). "We investigated the connection between immune cell infiltration and MPP7 expression in various cancer types using algorithms such as CIBERSORT, CIBERSORT-ABS, TIMER, EPIC, QUANTISEQ, TIDE, XCELL, and MCPCOUNTER to analyze data from TCGA." (PMID 39224268, 2024). "Nevertheless, further investigation is warranted to fully understand the pan-cancer function of MPP7 in tumorigenesis and its potential as a therapeutic target." (PMID 39224268, 2024). "Overall, our study suggests that MPP7 has the potential to be an effective target for immunotherapy to improve the health of cancer patients." (PMID 39224268, 2024). "Nevertheless, the potential correlation between MPP7 and the Rap1 signaling pathway and the possibility of MPP7 as a cancer therapeutic target warrant further investigation." (PMID 39224268, 2024). "In the present research, we used a range of bioinformatic tools to reveal abnormal MPP7 expression in human cancers." (PMID 39224268, 2024). "Consistent with previous research, the results from TCGA and GTEx show that MPP7 expression is lower in various cancers than in normal tissues." (PMID 39224268, 2024). "Cancer samples were assigned to high-expression groups and low-expression groups according to MPP7 expression." (PMID 39224268, 2024). "This analysis aimed to identify significant correlations between MPP7 expression and cancer progression." (PMID 39224268, 2024). "This research examined the potential prognostic value, expression, genetic mutations, immunomodulatory effects, protein phosphorylation, and relevant signaling of MPP7 in various cancers using comprehensive bioinformatics analysis methods." (PMID 39224268, 2024). "Mpp7 plays a role in the formation of tight junctions between epithelial and endothelial cells, which are crucial for cancer progression and metastasis, as well as in the apicobasal polarity in epithelial tissues." (PMID 36556285, 2022). "For cancer related genes, Nav3, Cenpf, Muc5Ac, Mpp7, Gas1, MageD2, Dusp1, Ros, Polr2a, Rragd, Ros1, and Hoxa9 are mutated." (PMID 32793490, 2020). "Finally, we conducted functional enrichment analysis to elucidate the possible mechanisms by which MPP7 influences cancer pathogenesis." (PMID 39224268, 2024). "Functional enrichment analysis of MPP7 co-expressed genes revealed that MPP7 may affect a variety of cancers through the Rap1 signaling pathway." (PMID 39224268, 2024). "Our research clarified the function of MPP7 in tumorigenesis from various perspectives, which provides a foundation for subsequent study on the specific mechanisms of MPP7 in the development and treatment of cancers." (PMID 39224268, 2024).
cancer (continued). "This comprehensive assessment underscores the significance of MPP7 in the prognosis of multiple cancers, its potential involvement in several less-studied cancers, the intrinsic molecular mechanisms of MPP7 in human cancer pathogenesis, and the significance of MPP7 in anti-tumor immune responses." (PMID 39224268, 2024). "Furthermore, MPP7 regulates the stability of several tumorigenesis-related proteins, thereby affecting cancer progression." (PMID 39224268, 2024). "Additionally, the MPP7 expression was significantly positively related to the invasion of cancer-related fibroblasts in BRCA, LIHC, STAD, THYM, and TGCT." (PMID 39224268, 2024). "Notably, MPP7 could be a possible prognostic and immune-related biomarker in cancer patients." (PMID 39224268, 2024).
tumor (4 papers, 2014 to 2025). "RT‐qPCR analysis demonstrated that, of nine TRmRNAs, DPEP1, FGF1 and MPP7 were largely expressed in normal tissues, whereas the other six mRNAs exhibited elevated expression levels in tumour tissues." (PMID 40673609, 2025). "Subsequently, confirming new targets for immunotherapy is crucial for improving clinical outcomes; however, the influence of MPP7 on the tumor immune microenvironment has rarely been explored." (PMID 39224268, 2024). "Nevertheless, the possibility that low MPP7 phosphorylation is an insignificant result of signal deregulation in tumor cells cannot be eliminated." (PMID 39224268, 2024). "The TCGA dataset was used as a reference to assess the relationship between MPP7 expression and tumor prognosis." (PMID 39224268, 2024). "In vivo, MPP7 knockdown reduced cell migration via the injection of tumor cells into the tail vein of nude mice." (PMID 36143417, 2022). "Variations in MPP7 were observed across multiple tumor tissues." (PMID 39224268, 2024). "•MPP7 expression is related to tumor immune cell infiltration." (PMID 39224268, 2024). "Known as tumor-associated macrophages (TAMs), they may sense hypoxia in tumor tissue and secrete VEGFs, basic fibroblast growth factor (bFGF), thymidine phosphorylase (TP), MMP-2, MPP-7, MPP-9 and MPP-12, and urokinase type plasminogen activator (uPA) to induce both hem- and lymphangiogenesis." (PMID 25254213, 2014). "We performed a comparative analysis of the phosphorylated MPP7 protein expression in 11 primary tumor tissues and their normal counterparts using UALCAN." (PMID 39224268, 2024).
bone disorder (1 paper, 2021). "Based on these reports, we consider MPP7 to be a good candidate for bone disorders in chickens." (PMID 34066823, 2021).
MPP7 also shares sentences with these, for which no sentence is quoted: breast invasive carcinoma (1 paper); cardiovascular diseases (1); cell squamous cell carcinoma (1); clear cell renal cell carcinoma (1); colon cancer (1); colorectal adenocarcinoma (1); glioblastoma (1); hepatocellular carcinoma (1); leiomyosarcoma (1); lung squamous cell carcinoma (1); Maturity-onset diabetes of the (1); multiple congenital anomalies (1); ovarian tumor (1); pancreatic adenocarcinoma (1); primary open angle glaucoma (1); rectum adenocarcinoma (1); testicular germ cell tumor (1); uterine carcinosarcoma (1); uterine corpus endometrial carcinoma (1).